MMP9 (matrix metallopeptidase 9)
Diseases named in the same sentence as MMP9 in open-access papers (continued):
Sharing a sentence is not in itself a finding about the gene and the disease.
tumor (continued). "Neutrophils are attracted to the tumor site by the hypoxic condition and active angiogenesis-inducing MMP-9, which, not being complexed with its inhibitor TIMP-1, has a stronger activity." (PMID 36497384, 2022). "Importantly, deflamin was effective in inhibiting MMP-2, MMP-9, and general ECM remodeling, favoring spatial constraints of tumor growth/progression and limited nutrient/oxygen supply, due to decreased angiogenesis." (PMID 36551666, 2022). "MMP9 displays substrate specificity for type-IV collagen and FN; it promotes epithelial-mesenchymal transition (EMT) by cleaving FN, thus enabling the release of transforming growth factor-β (TGF-β) and promoting tumor growth." (PMID 36147444, 2022). "Moreover, MMP-9 can be cleaved and activated by CTSK in acidic environments, such as tumor and bone resorption." (PMID 36005209, 2022). "For example, MMP9, ADAM10 and ADAM17 are involved in MICA shedding from tumor cells." (PMID 36114508, 2022). "To further investigate if this trend is due to the strong heterogeneity of the GBM tissue, we explored the connection between ADAM8, MMP9, and miR-181a-5p in a pilot experiment using MR-spectroscopy guided surgery at different locations in a GBM tumor tissue sample of one selected patient." (PMID 35371977, 2022). "Matrix metalloproteinase-2 (MMP-2) and MMP-9 cleavage by SCUBE3 releases fragments, which can bind to transforming growth factor-b (TGF-b) type II receptors, thereby activating the TGF-b signal transduction and promoting tumor development." (PMID 35663937, 2022). "MMP-9, as a cancer biomarker, participates in ECM degradation and facilitates tumor aggressiveness." (PMID 36117852, 2022). "In miR-18a high samples, 11/13 samples (85%) expressed high levels of MMP9 as opposed to 11/41 (27%) of miR-18a low tumor specimens (p < 0.0001)." (PMID 35626709, 2022). "Tumor and stromal cells are not the only sources of VEGF in NETs, as tumor-infiltrating neutrophils have been shown to mobilize latent VEGF from the extracellular matrix through the release of metalloproteinase 9 (MMP-9), at least in mice." (PMID 36059642, 2022). "As we discuss, activating β-ARs may result in anti-tumor effect (upregulate Cx43 protein levels) or pro-tumor effect (upregulate MMP-2 and MMP-9 levels)." (PMID 36010960, 2022). "They further identified that TANs also perform autophagy via the synergy of ERK1/2, p38 and NF-κB signaling axis and subsequently facilitate tumor progression by enhancing the secretion of OSM and MMP9, suggesting a regulatory loop between tumor cells and neutrophils." (PMID 36093115, 2022). "Collectively, these results suggested that PPARγ has a critical function in the terminal differentiation of MMP9+ TAMs in HCC, which could promote HCC progression through inducing HCC cells migration, invasion, and tumor angiogenesis." (PMID 35933472, 2022). "It is recognised that mast cell function in cancer can be tumour stage dependent, for example in promoting early but not late stage prostate cancer growth through MMP9 production." (PMID 36263033, 2022). "In addition to VEGF, ESM1 promoted MMP9, DLL4, and ICAM3 expression, indicating that ESM1 cooperated with VEGF to promote tumor development and promote bevacizumab resistance." (PMID 36428773, 2022). "Functionally, circ-MMP9 knockdown could weaken the metastasic and invasive abilities of OSCC tumor cells in vitro and inhibited lung metastasis in vivo." (PMID 36091137, 2022). "Tumor cells exploit this inflammatory environment to invade, proliferate and sustain angiogenesis, by producing vascular endothelial growth factor (VEGF), Bv8, and MMP9." (PMID 34084145, 2021). "Similarly, neutrophil granulocytes in the tumor microenvironment secrete VEGF and MMP-9, thereby enhancing the development of new vessels." (PMID 34821752, 2021). "The production of MMP-9 and uPA, which are ECM-degrading enzymes, is up-regulated by neoplasm." (PMID 33968773, 2021).
tumor (continued). "In addition, CTP/CDDP enhanced the expression of RKIP and inhibited the HIF-1α/MMP9 pathway by releasing NO and COS in hypoxic cells, thus inhibiting the EMT process of tumor and enhancing the anti-metastatic effect of chemotherapeutic drugs." (PMID 34399762, 2021). "In PTC patients, 131I therapy almost halved the imbalance between MMP-9 and TIMP-1 and this decrease may reduce tumor cell viability and migratory potential." (PMID 34298820, 2021). "For example, MMP-9 and MMP-2 cleave TGF-b, promoting tumor invasion, and angiogenesis." (PMID 34446834, 2021). "MMP-9, and -2, and urokinase plasminogen activators play a crucial role in degrading the ECM and enabling metastatic cells to enter the vasculature and move into the target organ, resulting in tumor metastasis of cervical malignancies." (PMID 34912809, 2021). "In addition, immunohistochemistry on tumor sections from the xenograft models showed that both individual treatment and co-treatment decreases the protein expression levels of Ki-67, VEGFR, MMP9, HIF1-α and CXCR4 compared to control tumors." (PMID 33673143, 2021). "This study suggests that the profiling of tumor-based interaction between AR, ki67, VEGF, HIF1beta and MMP9 in epithelium and stroma may be a significant contribution in the personalized diagnostics of OSSC." (PMID 33920263, 2021). "Moreover, in the morphologically normal tissue adjacent to the tumor, significant expression of MMP-1, MMP-2, and MMP-9 was found, which additionally contributes to an increase in the destructive potential of the tumor." (PMID 34830452, 2021). "Similarly, other studies have shown that MMP9 and CTSS inhibitors effectively inhibit tumor growth as well." (PMID 34771678, 2021). "In addition, the coordinating action of MMP-2 and MMP-9 have been identified as contributing factors to ECM degeneration, photoaging, and tumor progression." (PMID 33925954, 2021). "This stimulates the expression of matrix metalloproteinase 9 (MMP9), resulting in tumor invasion." (PMID 33920054, 2021). "Further experimental results highlighted that luteolin significantly reduced tumor growth of A375 cells in a mouse xenograft model, confirming that the antitumor activity is derived from down-regulation of MMP-2 and MMP-9 expression through the PI3K/Akt pathway." (PMID 34208196, 2021). "Therefore, inhibiting the expression of MMP-2, MMP-9, and MMP-1 is important to prevent tumor invasion and metastasis." (PMID 33833342, 2021). "Furthermore, the inhibition of KLF5 markedly decreased MMP-2, MMP-9 and VEGF, which further confirms the role of KLF5 not only in tumor growth, but also in migration and angiogenesis and overall metastatic potential of PTC cells." (PMID 33430300, 2021). "MMP2, MMP9 and MMP13 are prominent enzymes that promote tumor cell invasion and migration and regulate the progress of epithelial-to-mesenchymal transition (EMT), which is a transformation process of the epithelial cells to the mesenchymal cells and can promote cancer metastasis." (PMID 34820358, 2021). "Analysis with TIMER showed strong correlation between NRP1 expression and the abundance of tumor progression-related genes, MMP1, MMP3, MMP9, VEGFC, FLT4 and CXCL12 in LUSC, while there isn’t clear association between NRP1 expression and this panel of pro-tumorigenic genes in LUAD." (PMID 34168096, 2021). "Although we did not evaluate macrophage phenotype, VEGF-A, MMP-2, and MMP-9 levels reflect tumor microenvironment changes as they are produced by M2 macrophages." (PMID 34194604, 2021).
tumor (continued). "It has been shown that some members of the family of MMPs promote tumor growth, angiogenesis, epithelial–mesenchymal transition (EMT), and premetastatic niche formation in cancer patients, as is the case with MMP-1, MMP-2, MMP-3, and MMP-9." (PMID 34445715, 2021). "In addition, the selection pressure when subjected to hypoxia leads to the survival of more malignant subpopulations of tumor cells expressing MMP-2, MMP-9, and VEGF." (PMID 34194604, 2021). "Using conventional tumor section immunofluorescence, CRC lung nodules exhibited PRISM localization concentrated at the tumor periphery, and colocalized with expression of a key ECM regulator, MMP9." (PMID 34267368, 2021). "Our results show a significantly higher mRNA expression of MMP1, MMP9, POSTN, GREM1, FMOD, and COL1A2 in tumor biopsies compared to normal tissue, but the significant difference between responder and non-responder groups was only found for the expression of FMOD mRNA." (PMID 34283070, 2021). "In summary, PLAU promotes tumor cells proliferation and migration via MAPK/MEK/Erk/Slug/MMP9." (PMID 33574243, 2021). "In BC patients, high tumor levels of SIRT6 were shown to enhance BC cell resistance to chemotherapeutics and to promote BC survival, migration, and invasion through the expression of cyclin D1, NF-κB, β-catenin, and matrix metalloproteinase 9 (MMP9)." (PMID 33482921, 2021). "To assess whether expression of these MMPs and collagen I in combination with LAIR-1 impacts survival, we performed bioinformatic analyses of tumor MMP1, MMP9, COL1A1 and LAIR1 mRNA expression using data from the TCGA database." (PMID 34691040, 2021). "ALOC-EO-treated, but not control B16F10 tumor-carrying mice showed lower total MMP9 plasma levels and a lower MMP7 and MMP9 gene expression in extracted tumors." (PMID 34360915, 2021). "Moreover, gene set enrichment analysis revealed that MMP9 and IGFBP1 were involved in tumor immune via mediating cell surface receptor signal pathway, cytokine production pathway, or monocyte signal pathway." (PMID 33758602, 2021). "As exhibited by immunohistochemistry, the positive rates of SALL4, MMP-2, MMP-9, and PCNA proteins were decreased in tumor tissues of mice treated with exosomes, and these trends were further facilitated in the tumor tissues of mice treated with miR-15a agomir-exos." (PMID 34455417, 2021). "In addition, when PRISM was used to perform longitudinal tracking of tumor progression in individual animals, the 64Cu-PRISM PET measurement of liver tumor expansion matched a corresponding increase in MMP9-cleavable reporter signals over time." (PMID 34267368, 2021). "Before tumor cells reach premetastatic sites, MDSCs significantly decrease IFN-γ levels; increase proinflammatory cytokine and matrix metalloproteinase 9 (MMP9) production; and promote vascular remodeling, thereby forming an inflammatory and immunosuppressive environment." (PMID 34403220, 2021). "On the other hand, MDSCs could also participate in the remolding process of the tumor microenvironment and tumor angiogenesis via VEGF, bFGF, and MMP9." (PMID 34497832, 2021). "In the present study, MMP-9 is not only a marker of inflammation: it has a major role both in opening the way to cancer cells by digesting the extracellular matrix (ECM) all around them and to provide the neo-vasculature necessary to support tumor metastasis." (PMID 35723387, 2021). "It is well known that overexpression of MMP-9 in NPC could facilitate local invasion and tumor growth, indicating that MMP-9 plays a role in the progression of NPC tumor invasion and metastasis." (PMID 34078895, 2021). "MMP1 and MMP9 were not upregulated in tumor cells co-cultured with CAFs in 2D, but these MMPs were upregulated in tumor tissue from HNSCC patients compared to normal oral tissue." (PMID 34283070, 2021). "Our pre-surgery data showed that neither salivary MMP-9 nor 8-OHdG had any significant difference according to tumor location and TNM staging." (PMID 33735248, 2021).
tumor (continued). "In one study of gastric adenocarcinoma, both uPA and MMP-9 mRNAs were shown to be expressed in 58% of tumours, but co-expression was not explored." (PMID 34439251, 2021). "M2 TAMs produce arginase 1 (ARG1), IL-10, transforming growth factor-beta (TGF-β), vascular endothelial growth factor (VEGF), matrix metallopeptidase 9 (MMP9) and prostaglandin E2 (PGE2), thus subverting anti-tumor adaptive immunity and promoting tumor development and spreading." (PMID 34572009, 2021). "In addition, the expressions of MMP2 and MMP9 in TNBC cells has also been further detected, which were considered to have a high correlation in tumor migration and invasion events." (PMID 34858165, 2021). "MMP-9 and MMP-2 are essential to cleavage of collagen type IV, the major component of the basement membrane, and in the context of cancer biology, they are activated at the onset of angiogenesis, resulting in invasive tumor growth." (PMID 33716674, 2021). "The main mechanism of the proangiogenic properties of CCL2/MCP-1 is the recruitment of monocytes into the tumor niche, which are transformed into TAM, which secrete VEGF-A but also other proangiogenic factors such as matrix metalloproteinase 9 (MMP-9) and PGE2." (PMID 34639040, 2021). "The authors suggest that the oncogenic effect of MMP-9 in this type of tumor is not due to its elevated expression but to decreased inhibition by TIMP-1, whose expression is significantly reduced." (PMID 35097136, 2021). "In addition, an immunohistochemical study of MMP-9, -11, and -14 TIMP-1 and -2 expression by cell types at the invasive tumor front was carried out." (PMID 33669393, 2021). "TANs may be a critical source of MMP-9, which can promote vascular endothelial growth factor (VEGF) activation and tumor angiogenesis." (PMID 34540678, 2021). "miRNA345 silences the production of KISS1, which can lead to the upregulation of proangiogenic VEGF, pro-invasive MMP9 and SLUG, EMT-related E-cadherin, autophagy-related ATG5, LC3-II, and p62/SQSTM1, to ultimately promote tumor cell adaptation and propagation in the brain." (PMID 33466236, 2021). "To explore the anti-tumor effect of ProIFN, we first determined the expression levels of tumor-enriched enzymes such as MMP-2, MMP-9, MMP-11, MMP-14, fibroblast activation protein alpha (FAP), and urokinase plasminogen activator (uPA) in a variety of tumor lines." (PMID 34620867, 2021). "In addition to immunosuppressive mechanisms, MDSCs promote tumor progression by affecting the tumor microenvironment through the production of VEGF, basic fibroblast growth factor (bFGF), and MMP-9." (PMID 34445235, 2021). "Tumor-secreted GM-CSF, CXCL12, and CCL2 attract monocytes to the TME and drive their differentiation into M2 TAMs, which then promote angiogenesis through secretion of Matrix Metalloproteinase 9 (MMP9) and Vascular Endothelial Growth Factor A (VEGF-A)." (PMID 34830776, 2021). "Moreover, Bai was tested in a pancreatic neuroendocrine tumor cell line (BON1 cells), and the observed reduction of tumor migration and invasion related to the decreased MMP-2 and MMP-9." (PMID 33498927, 2021). "Western blot result revealed that oe-ADAMTS9-AS1 markedly decreased the expression of tumor markers for proliferation and invasion, such as Ki67, PCNA, MMP-2, MMP-9, suggesting that oe-ADAMTS9-AS1 could reduce tumor proliferative, and invasive abilities." (PMID 34900984, 2021). "IHC of WNT5A in extracranial metastatic lesions revealed none-to-weak positivity but MMP9 IHC showed occasional tumor cells with strong cytoplasmic immunoreactivity." (PMID 33799999, 2021). "Based on our results, we can suggest greater utility of serum TIMP-1 compared with MMP-9, MMP-2, and TIMP-2 in the diagnosis of CRC, particularly in the assessment of the tumor stage, survival of cancer patients, resectability of the tumor, and in the differentiation between CA and CRC." (PMID 34071492, 2021).
tumor (continued). "Likewise, decreased levels of metalloproteinase MMP9 and ADAM8 also shrank tumor progression on this basis." (PMID 34298635, 2021). "As suggested above, MMP-9 from TANs may increase the bioavailability of VEGF-A for VEGFR2 on endothelium in this model, thus working together with TAMs to remodel the tumor vasculature." (PMID 35008355, 2021). "Various components in NETs, such as: MMP-9, CG, and NE, can induce the expression of vascular endothelial growth factor (VEGF) to promote tumor growth, metastasis and angiogenesis." (PMID 34869390, 2021). "MMP9, a 92 kDa protein with protease activity, is one of the most active enzymes in the MMP family for the degradation of type IV collagen and plays an important role in tumor vascularization, invasion of tumor cells, and metastasis." (PMID 34307654, 2021). "In PDAC, tumor-derived arachidonic acid induces TAMs to produce immunoinhibitory and tumor-supporting molecules such as PGE2, VEGF, monocyte chemoattractant protein-1 (MCP-1), IL-6, and matrix metallopeptidase (MMP)-9." (PMID 34988072, 2021). "Association between the expression of EMT-related genes (specifically MMP2 and MMP9) and lncRNAs MALAT1 (study performed on OC tumor tissue samples (n = 64) and reference tissue (n = 30)) and TP73-AS1 (study done on 60 pairs of OC tumor/control tissue) was observed." (PMID 33921525, 2021). "Selenite inhibits the invasion of tumor cells via decreasing expression of MMP-2, MMP-9, and uPA." (PMID 34065478, 2021). "IL-6 is also upregulated in the tumor microenvironment, where it activates two signaling pathways: (i) JAK2/STAT-3, which induces EMT (upregulation of E- and N-cadherin, MMP7, and MMP9) and increases the metastatic potential; (ii) PI3K/Akt, which promotes cancer cell survival." (PMID 33670492, 2021). "The results suggested that decreased WNT5A expression, together with increased MMP9 expression, in icSFT/HPC, may affect vascular tightness and prompt tumor cells to metastasize extracranially." (PMID 33799999, 2021). "In addition, miR-765 mimics obviously down-regulated the expression of several EMT-related markers (e.g., COL3A1, FN1, CDH2, S100A4, MMP9, SNAIL and ZEB1) and up-regulated TJP1 expression in tumor lesions." (PMID 33859750, 2021). "In addition to IL-8, migration inhibitory factor (MIF) from tumor cells induces CXCR2-dependent chemotaxis, improved neutrophil survival, and release of CCL4 and MMP-9, helping develop aggressive HNSCC phenotype." (PMID 33925575, 2021). "In response to hypoxia, PC tumour cells produce several angiogenic molecules, including hypoxia-inducible factors (HIFs), vascular endothelial growth factors (VEGFs), FGFs, PDGF, Matrix metallopeptidase 9 (MMP-9), and interleukin-8." (PMID 34336679, 2021). "They promote tumor initiation, by the production of reactive oxygen species (ROS) and reactive nitrogen species (RNS), as well as the proliferation of tumor cells by the secretion of neutrophil elastase (NE) and matrix metalloproteinase 9 (MMP9)." (PMID 35008790, 2021). "At mRNA level, there was a significant decrease of MMP-9 in tumors from ILEI KD cells and quantification of MMP-9 immunohistochemistry in tumor sections showed a similar trend with a significant difference between the shCont tumors and those with ILEI KD and crizotinib in combination." (PMID 33596971, 2021). "ECs can influence ECM remodeling either by the expression of MMPs such as MMP2 and MMP9 or by the release of cytokines like CCL2, IL-8 and CXCL16, which act in a paracrine manner by upregulating the expression of MMPs in other cell types, such as tumor cells." (PMID 34073394, 2021). "CAFs may also be involved in tumor escapes from the immune response by releasing MMP-2, MMP-9 and MMP-14." (PMID 34204372, 2021). "Similarly, mRNA levels of vimentin, N‐cadherin, E‐cadherin, CK‐19, MMP‐9, and MMP‐2 in tumour tissues were consistent with the gene expression results in Linc00485‐silenced A549 cells." (PMID 33237626, 2021).